MPO (myeloperoxidase)
Diseases named in the same sentence as MPO in open-access papers (continued):
Sharing a sentence is not in itself a finding about the gene and the disease.
colitis (continued). "Neutrophils also contained EPRAP; however, EPRAP deficiency did not alter myeloperoxidase activity in the colonic tissues of DSS-treated mice, suggesting that EPRAP deficiency in neutrophils does not play a major role in enhancing colitis and colitis-associated tumorigenesis." (PMID 26439841, 2015). "Cucurbitacin IIb also did not affect the content of colonic MPO and EPO, impairment of colonic morphology and histological index of colitis in those mice treated with antibiotics." (PMID 39347394, 2024). "In contrast to pharmacological inhibition studies targeting MPO, herein MPO KO mice challenged with DSS revealed poor clinical and histopathological outcomes, with no observed protection from acute experimental colitis." (PMID 38673843, 2024). "When compared to the negative control group, the colitis-induced rats had a significant decrease (P < 0.0001) in TAC levels, a significant increase (P < 0.0001) in MPO and MDA levels, and a significant decrease (P < 0.001) in GSH levels." (PMID 35428860, 2022). "The levels of COX, MPO, and PGE2 were significantly decreased in colitis rats fed with feed containing beta-glucans compared to rats with colitis fed with feed without beta-glucans at both time points." (PMID 33923129, 2021). "Surprisingly, no action on MPO activity was found in TNBS-induced animal models, while in DSS-induced colitis KR-12 decreased this marker of neutrophil infiltration." (PMID 33219923, 2021). "On the other hand, RES had no significant impact on MPO activity and levels of TNF-α, PGE2, IL-6 and IL-10 in mouse models of DSS-induced colitis." (PMID 32722619, 2020). "Rats with TNBS-induced colitis had significantly elevated DAI, CMDI, histological colonic damage score, and MPO activity (all P < 0.001) compared to rats without colitis." (PMID 26718757, 2015). "To determine mild or severe signs of colitis in mice lacking TNF-R1 or 2 are partially attributed to decreased or increased infiltrate of neutrophil, we detected the levels of MPO, indices for neutrophil infiltration, in the colon 8 days after DSS." (PMID 23285227, 2012). "Our findings obtained in the DSS model of colitis confirmed that stimulation of FFAR4 significantly alleviated macroscopic parameters of colitis, with no apparent effect on the MPO activity, which suggests weak or perhaps lack of the effect on neutrophil infiltration." (PMID 34444876, 2021). "However, IL-1β, TNF-α, IgG, SOD, and MPO were not significantly affected by Gln, indicating that Gln is not so effective as Ala-Gln to suppress DSS-induced colitis." (PMID 34046146, 2021). "Unexpectedly, the rSjcystatin, if given to mice before TNBS induction, failed to decrease the levels of DAI, MPO and other inflammation indexes compared to the mice with colitis, suggesting an unascertainable preventative effect of rSjcystatin on TNBS-induced colitis." (PMID 26728323, 2016). "In TNBS-induced colitis group, a moderate correlation was detected between MPO activity and the number of TLR9-positive cells (r = 0.654, P < 0.001) and a low non-significant correlation between MPO activity and TLR9 gene expression (r = 0.394, P = 0.057)." (PMID 26718757, 2015). "MPO activity, as the marker of neutrophil infiltration of colonic mucosa which corresponded with the intensity of inflammation, was significantly increased in the colonic mucosa of TNBS colitis (P < 0.02) as compared with MPO activity in rats without colitis." (PMID 25684862, 2015). "Furthermore BTZO-15 reduced the ulcerated area and rectal MPO activity in 2,4,6-trinitrobenzene sulfonic acid (TNBS)-induced colitis rats without affecting rectal TNF-α levels." (PMID 21853095, 2011). "Although we did not detect the presence of MPO-DNA complexes in the plasma that was reported in mice received 3.5% DSS for 6 d, colonic homogenates of mice with 2.5% DSS-induced colitis contained significantly more MPO-DNA complexes than colonic homogenates of the control mice." (PMID 32764411, 2020).
vasculitis (329 papers, 2001 to 2026). "In contrast, IgG from patients with hydralazine-associated ANCA vasculitis showed similar affinity to both types of MPO." (PMID 40020049, 2025). "Myeloperoxidase (MPO)-antineutrophil cytoplasmic autoantibodies (ANCA)-associated vasculitis often leads to life-threatening alveolar hemorrhage or fibrosis." (PMID 39906123, 2025). "Based on our in vitro and ex vivo data demonstrating the association of hydralazine-modified MPO with development of ANCA-vasculitis, we sought direct evidence that hydralazine-modified MPO is pathogenic." (PMID 40020049, 2025). "In Japanese patients with MPO‐ANCA‐associated vasculitis (JMAAV), a refractory vasculitis study group determined the efficacy of a severity‐based treatment protocol for MPO‐ANCA‐positive AAV (MPO‐AAV)." (PMID 40070290, 2025). "Eosinophilic granulomatosis with polyangiitis (EGPA) is a multifaceted diseased vasculitis typically associated with myeloperoxidase-perinuclear-anti-neutrophil cytoplasmic antibody (+MPO-P-ANCA)." (PMID 40206908, 2025). "Myeloperoxidase (MPO) antibodies are present in around 60%–80% of those with MPA are associated with a higher risk of development of vasculitis among those with interstitial lung disease (ILD)." (PMID 40641494, 2025). "In 2022, it was reported that CD16+ monocytes were significantly decreased in the blood but increased in glomeruli of patients with myeloperoxidase-antineutrophil cytoplasmic antibody (ANCA)-associated vasculitis (MPO-AAV) compared with healthy controls." (PMID 40508161, 2025). "Sera from patients with LAC-associated vasculitis also induced DNA and MPO release from neutrophils with a pattern morphologically compatible with NETosis although to a lesser degree than the cocaine-levamisole mixture." (PMID 38434602, 2024). "Left untreated, MPO vasculitis with renal involvement poses a mortality risk of up to 90%, underscoring the significance of prompt detection and corticosteroid intervention to avert renal failure and improve patient outcomes." (PMID 38357081, 2024). "This study suggests that a low serum ceruloplasmin level at diagnosis of anti-MPO ANCA-associated vasculitis is associated with a worse survival." (PMID 39388433, 2024). "The diagnosis was confirmed by broncho-alveolar lavage and was secondary to p-ANCA–associated vasculitis with >14,796 arbitrary units (A.U.)of anti-myeloperoxidase antibodies detected (normal value [n.v.] <20 A.U.)." (PMID 38953896, 2024). "Our data confirm that low ceruloplasmin levels are associated with worse outcome in patients with anti-MPO vasculitis." (PMID 39388433, 2024). "In the present work, patients with LAC-associated vasculitis, confirmed by skin biopsy, were positive for ANCAs (92%), anti-MPO antibodies (64%), or anti-PR3 antibodies (28%)." (PMID 38434602, 2024). "Of the 1830 patients with ANCA-associated vasculitis evaluated during the study period, 251 patients had MPO-ANCA–associated vasculitis with active kidney involvement." (PMID 36526414, 2023). "Our study characterizes how MPO-ANCA status relates to the risk of relapse and how serial MPO-ANCA measurements can prove useful for remission-maintenance treatment decisions in patients with MPO-ANCA–associated vasculitis with GN." (PMID 36526414, 2023). "The authors showed that achievement of ANCA negativity at the time of remission was associated with a reduced risk of relapse.41, –43 ANCA status appears to correlate with relapse risk, particularly in patients with MPO-ANCA–associated vasculitis with GN." (PMID 36526414, 2023). "We experienced a case of myeloperoxidase antineutrophil cytoplasmic antibody (MPO-ANCA)-associated vasculitis after Moderna COVID-19 vaccination." (PMID 37101523, 2023). "Our results suggest that continued serial MPO-ANCA monitoring in patients with MPO-ANCA–associated vasculitis with GN can be used to guide remission-maintenance treatment." (PMID 36526414, 2023).
vasculitis (continued). "In ANCA-associated vasculitis, the presence of proteinase 3, MPO and lysosome‐associated membrane protein 2 antibodies can stimulate neutrophils to release NETs, exacerbating the injury caused by vasculitis." (PMID 37478141, 2023). "Our study corroborates and expands on the prior observations suggesting that serial ANCA determinations are useful to gauge the relapse risk of patients with MPO-ANCA–associated vasculitis with GN." (PMID 36526414, 2023). "EGPA is classified as an antineutrophil cytoplasmic antibody (ANCA)-associated vasculitis, with myeloperoxidase-ANCA detected in approximately one-third of the patients." (PMID 37762936, 2023). "In an MPO-ANCA transfer mouse model, C4-deficient mice develop vasculitis after injection of anti-MPO IgG, whereas C5- and factor B-deficient mice are resistant to the development of vasculitis." (PMID 37781373, 2023). "Common adverse reactions to mRNA vaccines against COVID-19 include pyrexia and general malaise, but MPO-ANCA-associated vasculitis can also occur." (PMID 37101523, 2023). "ILD occurred in one-fifth of Korean patients with AAV in this study and was associated with MPA and MPO-ANCA vasculitis." (PMID 35655922, 2022). "Anti-neutrophil cytoplasmic antibody (ANCA)-associated vasculitis is characterized by small vessel inflammation and the presence of autoantibodies against cytoplasmic proteases, most often proteinase-3 and myeloperoxidase." (PMID 35445945, 2022). "Silica: Occupational silica exposure, related to mining, construction work, farming and agriculture, has been recognized as a risk factor for MPO-ANCA vasculitis." (PMID 36294902, 2022). "MPO positivity was seen in a case of phenytoin-associated vasculitis, which was treated successfully with steroids and cyclophosphamide." (PMID 36419545, 2022). "There were ten cases with new-onset ANCA vasculitis, including 3 cases associated with proteinase 3 (PR3) and 7 cases of myeloperoxidase (MPO)-associated vasculitis, while six cases were ANCA vasculitis relapses." (PMID 36366292, 2022). "MPO released extracellularly causes MPO cytoplasmic antibody (MPO-ANCA)-associated vasculitis, leading to a vicious cycle of inflammation." (PMID 35396366, 2022). "Passive transfer of MPO autoantibodies into recipient mice cause glomerulonephritis and vasculitis and provides further proof that these autoantibodies are pathogenic." (PMID 33763057, 2021). "We were interested in examining the phenotype of VISTA deficient mice in anti-MPO vasculitis in case VISTA was important through other additional mechanisms." (PMID 36751530, 2021). "The role of the increase in or testing positive again for ANCAs as a predictor of a relapse, which has long been controversial, now seems to have greater consensus: Anti-MPO ANCAs are less often associated with a relapse of vasculitis than anti-PR3 ANCAs." (PMID 33372616, 2020). "An 81-year-old man undergoing treatment for interstitial pneumonia developed a high fever and was diagnosed with ANCA-associated vasculitis based on an elevated myeloperoxidase- (MPO-) ANCA titer and renal biopsy findings." (PMID 32695547, 2020). "The detection of NETs in lesions of patients suffering from MPO-antineutrophil cytoplasmic antibody (ANCA) associated vasculitis (MPO AVV) suggested an additional role of NETs in this autoimmune condition." (PMID 32085405, 2020). "In a murine model of MPO-ANCA vasculitis, C5aR-deficient mice injected with anti-MPO IgG were protected from disease to a higher degree than wild type mice (5 out of 6)." (PMID 31216309, 2019). "The pathogenic importance of MPO-ANCA is supported by the ability of these antibodies to induce a vasculitis syndrome resembling AAV when MPO-ANCA are transferred into experimental mouse models." (PMID 31867013, 2019). "The PPI networks among genes mapping to PR3-ANCA and MPO-ANCA vasculitis-associated SNPs showed closer connections." (PMID 30795559, 2019).
vasculitis (continued). "No noteworthy variants were observed in MPA, but genetic variants related to the HLA-DR and HLA-DQ loci were found to be associated with MPO-ANCA vasculitis." (PMID 30795559, 2019). "We have focused this study on the subgroup of MPO vasculitis because MPO are more often associated with crescentic glomerulonephritis, renal involvement, failure to obtain complete remission and poorer renal outcome." (PMID 31088509, 2019). "This study shows a partial efficacy of rituximab in renal function recovery and a low risk of infectious complications in patients with MPO vasculitis with severe renal involvement, in particular in the short term." (PMID 31088509, 2019). "Transfer of MPO-ANCA generated from MPO-knockout mice immunized with mouse MPO induces glomerulonephritis and vasculitis in susceptible mice." (PMID 28620373, 2017). "We next examined if this intracellular C5a was important in pathogenesis and constructed four groups of bone marrow chimaeric mice from wild‐type or C5‐deficient donors and recipients, and induced anti‐MPO vasculitis." (PMID 27235854, 2016). "Myeloperoxidase (MPO)-specific ANCA-associated vasculitis is more widely known than proteinase 3 ANCA-associated vasculitis in Japan." (PMID 27099135, 2016). "Our present study found a close association between CFH and renal damage in patients with MPO-ANCA-positive vasculitis." (PMID 25994214, 2015). "Our patient had mild increase in antiphospholipid antibodies similar to the MPO associated vasculitis patient." (PMID 25097791, 2014). "Serial measurement of MPO-ANCA is recommended in patients with PF as ANCA positivity suggests increased risk of vasculitis and also to monitor disease activity once AAV develops." (PMID 25279305, 2014). "Positive ANCA test associated with anti MPO or anti PR3 antibodies with clinical evidence of vasculitis is rare in SSc patients." (PMID 25279305, 2014). "Antibodies associated with hydralazine-induced vasculitis include MPO ANCA, ANA, anti-histone antibody, anti-elastase antibody, and anti-phospholipid antibody." (PMID 25210633, 2014). "In fact, we found significantly decreased anti-cPR3m reactivity in PR3-ANCA-associated vasculitis patients, compared to both HC and MPO-ANCA patients." (PMID 21437233, 2011). "Animal model studies provided some evidence of a direct pathogenic effect of passively transferred MPO and proteinase 3-specific ANCAs in inducing pauci-immune glomerulonephritis and vasculitis." (PMID 23283308, 2008). "MPO is a major autoantigen in vasculitis associated with antineutrophil cytoplasmic antibodies (ANCA)." (PMID 16677376, 2006). "Similar results were seen in a retrospective review of patients with MPO-ANCA vasculitis from the Mayo Clinic, whereby the risk of relapse was low even without maintenance therapy in patients with persistent MPO-ANCA negativity." (PMID 39927255, 2025). "Albeit anti-IgG and -IgM antibodies to MPO were present in all individuals with antineutrophil cytoplasmic antibody–associated (ANCA-associated) vasculitis, the increase in anti-MPO IgM in this patient cohort was higher compared with patients with nonhydralazine-mediated vasculitis." (PMID 40231470, 2025). "Similarly, CRP and MPO-ANCA were incorporated as explanatory variables based on their known associations with vasculitis severity and renal prognosis." (PMID 40136450, 2025). "Diagnostic tests revealed elevated MPO-ANCA levels consistent with vasculitis." (PMID 41295485, 2025). "Glomerular deposition of C3 in MPO-ANCA-vasculitis has been associated with worse renal outcomes." (PMID 40430184, 2025). "Sera from patients with LAC-associated vasculitis can induce IL-8 synthesis, which may be due to their anti-MPO content." (PMID 38434602, 2024).
vasculitis (continued). "For example, antibodies that recognize the neutrophil proteins proteinase 3 (PR3) and myeloperoxidase (MPO) are associated with vasculitis and have been shown to stabilize extruded chromatin content from neutrophils called neutrophil extracellular traps (NETs)." (PMID 38652559, 2024). "Moreover, it would explain the predominance (92%) of circulating ANCAs and anti-MPO antibodies in the group of patients with LAC-associated vasculitis." (PMID 38434602, 2024). "Furthermore, MPO-DNA has shown diagnostic value in anti-neutrophil cytoplasmic antibody-associated vasculitis." (PMID 39457503, 2024). "Because of its ability to inhibit MPO activity, we hypothesized that a low serum ceruloplasmin level could be associated with more severe vasculitis and worse prognosis." (PMID 39388433, 2024). "In addition, studying the effect of HLA alleles on disease outcome, for those who had MPO-ANCA-positive vasculitis, HLA-DRB1*0405 was associated with treatment failure." (PMID 37676628, 2024). "EGPA presents with a variety of clinical symptoms include asthma or allergic manifestations associated with marked eosinophilia, as well as organ damage associated with vasculitis, while only about 40% of patients produce the disease-labeled antibody myeloperoxidase (MPO)-ANCA." (PMID 37365612, 2023). "This was a retrospective cohort study of all patients with MPO-ANCA–associated vasculitis (microscopic with polyangiitis and granulomatosis with polyangiitis) and GN followed at the Mayo Clinic between 1996 and 2015." (PMID 36526414, 2023). "We analyzed 159 patients with active MPO-ANCA–associated vasculitis with GN." (PMID 36526414, 2023). "Indeed, MPO + ANCA EGPA seems to be an eosinophilic autoimmune disease more likely developing vasculitis and necrotising glomerulonephritis and an HLA-DQ association with MPO + ANCA-associated vasculitis." (PMID 36719484, 2023). "In addition, our study identified two hub genes which work as autoantigens in anti-neutrophil cytoplasmic antibody (ANCA)-associated vasculitis abnormally elevated in active renal involvement patients, including MPO and PRTN3." (PMID 36530895, 2022). "In the opinion of the authors, the mechanism of action of tofacitinib which involves activation by myeloperoxidase in neutrophils may have an association with the induction of ANCA-vasculitis." (PMID 34790443, 2021). "Anti-myeloperoxidase vasculitis was induced in wild type, factor B, or VISTA deficient mice." (PMID 36751530, 2021). "Recent investigations showed that the mechanisms by which MPO-ANCA IgG causes NETosis in people with vasculitis could be linked to the degree of antibody affinity rather than to the antibody levels 25,26,57." (PMID 33746569, 2021). "The role of the increase or testing positive again for ANCA as a predictor of a relapse, which has long been controversial, now seems to have greater consensus: Anti-myeloperoxidase ANCAs are less often associated with a relapse of vasculitis than anti-PR3 ANCA." (PMID 33372616, 2020). "In MPO-ANCA vasculitis, an association between proteinuria and kidney outcome was proposed and these patients may benefit from RAS inhibitors." (PMID 33023023, 2020). "Elevated serum levels of BAFF associate with PR3-and MPO-ANCA vasculitis." (PMID 33023023, 2020). "MPO+ ANCA EGPA is an eosinophilic autoimmune disease sharing certain clinical features and an HLA-DQ association with MPO+ ANCA-associated vasculitis, while ANCA-negative EGPA may instead have a mucosal/barrier dysfunction origin." (PMID 31719529, 2019). "Interestingly, the genes associated with interferon-gamma (IFN-γ)-mediated signaling pathway are highly enriched in both PR3-ANCA and MPO-ANCA vasculitis-associated SNPs (e.g., yellow nodes in the PPI networks)." (PMID 30795559, 2019). "In this sense, our patient may be suffering from a MPO-ANCA-associated vasculitis with ENT and renal disease." (PMID 28559644, 2017).